ADRB3 (adrenoceptor beta 3)
Diseases named in the same sentence as ADRB3 in open-access papers (continued):
Sharing a sentence is not in itself a finding about the gene and the disease.
Obesity (continued). "In summary, our meta-analysis indicated that the ADRB3 rs4994 polymorphism could significantly increase the risk of childhood and adolescent overweight/obesity, especially for the East Asia’s population." (PMID 32008426, 2020). "Whether the Adrenoceptor Beta 3 (ADRB3) gene rs4994 polymorphism could affect the individual risk of childhood and adolescent overweight/obesity remains controversial." (PMID 32008426, 2020). "ADRB3 is an obesity-associated gene that plays a key role in the regulation of energy balance." (PMID 33603663, 2020). "Although the mechanism responsible have not been elucidated yet, higher serum folic acid concentrations were associated with lower DNA methylation levels of ADRB3 gene in eutrophic individuals, which may represent a protective effect for obesity." (PMID 29866117, 2018). "Therefore, visceral fat area, rather than BMI, was thought to be the superior phenotype for testing the associations of UCP1/ADRB3 and obesity." (PMID 24086366, 2013). "In a forward stepwise logistic regression model that included obesity as a dependent variable and the polymorphism of the ADRB3 (with Trp64 allele as reference) and sex as independent variables, only the presence of the Arg64 allele reached statistical significance (OR 3.16; 95% CI 1.79-5.56)." (PMID 21992420, 2011). "Some variants of the ADRB3 gene may predispose subjects for the development obesity and metabolic abnormalities in the setting of modern sedentary lifestyle." (PMID 21992420, 2011). "Therefore, it has been suggested that the Trp64Arg variant of ADRB3 might predict the problems associated with weight loss by women with obesity." (PMID 35388349, 2022). "Consequently, these characteristics might have led to an insignificant relationship between the ADRB3 polymorphism and obesity‐related parameters in the present study; nevertheless, this polymorphism demonstrated a tendency to be associated with BMI." (PMID 35388349, 2022). "Moreover, glucose metabolism-associated genes, glucose-6-phosphatase (G6pc) and insulin-like growth factor binding protein 1 (Igfbp1), were down-regulated, accompanied with adrenoceptor β 3 (Adrb3) whose gene polymorphism is related to type 2 diabetes and obesity up-regulated." (PMID 34735568, 2021). "The ADRB3 rs4994 polymorphism (Trp64Arg), a T to C switch leading to the replacement of tryptophan by arginine at position 64, has been related to lower resting metabolic rate, weaker response to obesity treatment, and increased capacity to gain weight according to scattered evidence." (PMID 32008426, 2020). "Interestingly, this hypothesis is verified in this meta-analysis, since the data shows that the mutation C allele of ADRB3 is robustly associated with obesity the obesity is related to abnormal levels of adipokines." (PMID 32430022, 2020). "In addition, ADRB3 polymorphism Trp64Arg has been strongly associated to obesity and DM2." (PMID 29361938, 2018). "Interestingly, association of ADRB3 Trp64Arg gene polymorphism with obesity could only be observed in the rural, in particular in the female populations." (PMID 21619577, 2011). "Thus, approximately half of the studies found a positive association of the Trp64Arg polymorphism of the ADRB3 gene with obesity and IR, whereas the other studies didn't find any relationships between the presence of such polymorphism and obesity, type 2 DM or AH." (PMID 21992420, 2011). "On the basis of our previous finding that an HFD increased WWP1 expression, we propose that WWP1 is one of the candidates that negatively regulates lipolysis owing to decreased Adrb3 expression in WAT during obesity." (PMID 40362456, 2025). "On the basis of our results, we anticipate that co-treatment of inhibition of WWP1 expression and Adrb3 agonists will become a novel treatment for catecholamine resistance of obesity and diabetes." (PMID 40362456, 2025).
Obesity (continued). "Previously, we showed that mice lacking TBLR1 in white adipose tissue (WAT) exhibit impaired fasting‐induced lipolysis, partly due to reduced Adrb3 expression and signaling, rendering them prone to high‐fat‐diet‐induced obesity." (PMID 40787784, 2025). "These Adrb3 agonists have been developed by several pharmaceutical companies as treatments for obesity and type-2 diabetes but have yet to become successful." (PMID 40362456, 2025). "We anticipate that inhibition of WWP1 is a promising approach for a new treatment of obesity and type-2 diabetes using Adrb3 agonists." (PMID 40362456, 2025). "With age, the role of this ADRB3 genotype increases, which reflects the tendency for increased worldwide obesity prevalence in an aging society." (PMID 38397196, 2024). "To determine the genetic predisposition of this trait, we conducted an association analysis of SNPs of the genes encoding β3-AR (ADRB3) and uncoupling protein 1 (UCP1), which were previously reported to be associated with obesity and related traits." (PMID 38632325, 2024). "Specific polymorphism of ADRB3 gene—Trp64Arg impacts adipokines and lipid levels (mainly LDL-cholesterol) and is associated with obesity." (PMID 38397196, 2024). "Consistently, the m6A levels of adipose Adrb2, Adrb3, Atgl, and Cgi‐58 transcripts were substantially increased in obesity in both mice and humans." (PMID 37526326, 2023). "This suggests that normal weight adults with adequate levels of folate experience lower levels of ADRB3 gene methylation which can serve as a protective mechanism against obesity and altered lipid profiles." (PMID 36615885, 2023). "In a cohort of Northwest Mexican adults, single-nucleotide polymorphisms (SNPs) in the ABCA1 gene as well as FTO alpha-ketoglutarate-dependent dioxygenase (FTO), adrenoceptor beta 3 (ADRB3), and PPARG were associated with increased risk of obesity." (PMID 38027204, 2023). "Studies conducted in ADRB3-knockout mice concluded that diminished activity of ADRB3 led to abnormal lipolysis, increased lipid storage and obesity in the mice." (PMID 37899888, 2023). "In recent clinical trials, individuals with obesity and insulin resistance demonstrated improved oxidative metabolism and ameliorated glucose homeostasis following mirabegron (an ADRB3 agonist) treatment." (PMID 36483678, 2022). "Similar to ADRB2, ADRB3 expression decreases in adipocytes in patients with obesity and represents a mechanism whereby adipocytes become resistant to catecholamines in obesity." (PMID 36483678, 2022). "Among obesity‐related genetic factors in humans, the β3‐adrenergic receptor (ADRB3), which is mainly expressed in adipose tissue, plays an essential role in energy metabolism through thermogenesis and regulation of lipolysis in the adipose tissue." (PMID 35388349, 2022). "The SNP (rs4994) of ADRB3 gene has been extensively studied in obesity, type-2 diabetes, and other diseases pathogenesis and found that ADRB3 expression in bladder cells has been shown to be very high and promotes muscle relaxation." (PMID 34514165, 2021). "In particular, a number of studies has provided evidence regarding the relationship between β3-adrenergic receptors (ADRB3) and obesity." (PMID 34944408, 2021). "Polymorphisms in the three subtypes of β-adrenoceptor (ADRB1, ADRB2, and ADRB3 genes) show a correlation with obesity and body weight-related disorders." (PMID 33113859, 2020). "In contrast, in the liver, obesity led to higher expression of Pparα and Pparδ expression in older female livers compared to young females while ADRB3 stimulation led to downregulation of Pparα and Pparδ expression." (PMID 31983693, 2020). "In old male GWAT, the mRNA levels of Pparγ and Pgc1α involved in oxidative metabolism were downregulated with obesity and with ADRB3 stimulation." (PMID 31983693, 2020). "scRNA-seq was used to characterize immune cell populations during vWAT remodeling, either following ADRB3 stimulation or during diet-induced obesity." (PMID 33383883, 2020).
Obesity (continued). "Among these drugs, four drugs targeting ADRB3 are selected as possible therapeutic agents for the treatment of obesity, consistent with the biological process of “brown fat cell differentiation”." (PMID 31699147, 2019). "Some patients were carriers of polymorphisms PLIN4 -11482G > A-, fat mass and obesity-associated (FTO) -rs9939609 A/T- and β-adrenergic receptor 3 (ADRB3) -Trp64Arg." (PMID 29361938, 2018). "In contrast, lower gene expression of the ADRB3 gene in Caucasians and its relationship with higher propensity to obesity and related comorbidities are still controversial." (PMID 29866117, 2018). "In some populations, obesity and body weight related disorders show a correlation with polymorphisms in three subtypes of beta-adrenoceptor (β1, β2, and β3) [ADRB1, ADRB2 and ADRB3] genes." (PMID 29587766, 2018). "Additionally, there is indirect evidence that ADRB3 may participate in the regulation of body weight in humans, suggesting that epigenetic changes in the locus of the ADRB3 gene may be involved in the development of obesity and its associated metabolic complications." (PMID 29046732, 2017). "In a large number of studies, ADRB3 gene expression has been shown to be correlated with obesity in both humans and other mammals." (PMID 26290728, 2015). "Findings from various studies now provide a consistently clear picture of the important role of ADRB3 in the regulation of lipid metabolism and make this protein an obvious target for drug discovery strategies designed to treat obesity." (PMID 26290728, 2015). "Additional examples of polymorphisms that were found to be associated with both obesity and elite athletic performance are the ADRB2 Arg16Gly (rs1042713), and the ADRB3 Trp64Arg (rs4994)." (PMID 23573268, 2013). "After logistic regression analysis, including gender and ADRB3, the association was still statistically significant, but after including obesity in the list, ADRB3 lost its significance." (PMID 21992420, 2011). "If future investigations confirm these results, they may serve as a foundation for developing a new class of anti-obesity remedies that act via ADRB3." (PMID 41898705, 2026). "In addition, several previous studies have shown that obesity reduces Adrb3 expression and intracellular cAMP levels in adipocytes of WAT." (PMID 40362456, 2025). "Aberrant methylation of NPY, ADRB3, IGF1, and HIF3a have all been linked to obesity." (PMID 37899888, 2023). "Adipose Adrb2, Adrb3, Atgl, and Cgi‐58 transcript m6A contents are elevated in obesity." (PMID 37526326, 2023). "Furthermore, ADRB3 mediates the catecholamine-induced activation of adenylate cyclase and has anti-diabetes and anti-obesity effects." (PMID 35655232, 2022). "Whilst encouraging, the effects of ADRB3 agonists tested so far are considered modest and short lived, partly due to reduced ADRB3 expression and catecholamine resistance in the adipose tissue of individuals with obesity." (PMID 36483678, 2022). "Moreover, mutations in the gene encoding the β3-AR, ADRB3, have been correlated with insulin resistance, increased risk for obesity and diabetes, and nonalcoholic fatty liver disease in obese individuals." (PMID 34100382, 2021). "In addition to the ADRB3 gene, genes related to insulin resistance and obesity have been reported in Caucasians." (PMID 34347822, 2021). "Additionally, the obesity-related reduction in expression of beta-3 adrenergic receptor (ADRB3), responsible for lipolysis and thermogenesis, appeared significantly restored in mice upon addition of fucoxanthin to their high fat diet." (PMID 34444774, 2021). "Interestingly, in old female GWAT, the mRNA levels of Pparγ and Pgc1α were upregulated with obesity but downregulated with ADRB3 stimulation." (PMID 31983693, 2020). "Because of its demonstrated functions in lipid metabolism and observed gene expression dysregulation in obesity, ADRB3 could be reasonably expected to constitute a potential pharmacologic target for obesity treatment." (PMID 32008426, 2020).
Obesity (continued). "Molecular abnormalities in ADRB3 are related to the development of obesity and type 2 diabetes." (PMID 31929840, 2019). "Therefore, boosting the Adrb3 expression by means of TonEBP inhibition offers distinctive opportunity in therapeutic approach for obesity and metabolic diseases." (PMID 31387996, 2019). "Other examples of nsSNPs reported to be associated with obesity included leptin (LEPR) rs1805094 (Lys656Asn), beta-2 adrenergic receptor (ADRB2) rs1042714 (Glu27Gln), beta-3 adrenergic receptor (ADRB3) rs4994 (Trp64Arg), and vitamin D receptor (VDR) rs2228570 (Met1Thr)." (PMID 29755414, 2018). "Our present results shows for the first time that obesity and related disorders in Saudis are linked to polymorphism of Trp64Arg (rs4994) in ADRB3 gene but not to Arg389Gly (rs1801253) in ARDB1 gene." (PMID 29587766, 2018). "Thus, some polymorphism present in genes such as Fat mass and obesity-associated (FTO), Perilipin (PLIN) and β-adrenergic receptor 3 (ADRB3) have been studied associated with obesity development." (PMID 29361938, 2018). "Administration of GC and GNN reduce weight and improve lipid and glucose blood profiles in people with overweight or obesity, although the presence of polymorphisms PLIN4, FTO and ADRB3 might hinder in some degree these effects." (PMID 29361938, 2018). "Since in our previous report, we had observed an association between Gln27Glu polymorphism of ADRB2 gene, obesity, and other related disorders in Saudi population our interest was to explore if any association existed between ADRB1 (rs1801253) and ADRB3 (rs4994) and these abnormalities." (PMID 29587766, 2018). "On the other hand, it is relevant to mention that it was not detectable a relation between the methylation levels of the ADRB3 gene with overweight and obesity, since some studies have shown that these relations are more prominent in severe obesity (grade III e IV)." (PMID 29866117, 2018). "Alleles of both Glu27 in ADBR2 and Arg64 in ADRB3 are associated with obesity and/or non-insulin-dependent diabetes mellitus (NIDDM) in humans." (PMID 22937051, 2012). "This allowed us to accept ADRB3 as a candidate gene for obesity." (PMID 22550477, 2012). "Some studies had shown associations between obesity and Trp64Arg polymorphism of the ADRB3 gene, but not others." (PMID 21992420, 2011). "Theoretically the functional alterations in ADRB3 may promote the development of obesity and insulin resistance (IR)." (PMID 21992420, 2011). "The identification of the ADRB3-S100B signaling axis provides a mechanistic framework for understanding SCN-driven BAT regulation and opens new avenues for therapeutic strategies targeting metabolic disorders associated with circadian disruption, such as obesity and insulin resistance." (PMID 41343575, 2025). "ADRB3 dysfunction may lead to IR and obesity and may be a candidate gene for obesity and IR." (PMID 34512548, 2021). "With regard to the function of ADRB3 in energy intake, lipid profile, and folic acid levels, the study of epigenetic variation in this gene may contribute to a better understanding of the molecular basis of obesity and cardiovascular diseases." (PMID 30954083, 2019). "Therefore, an impairment of ADRB3 may lead to obesity through the energy expenditure reduction of fat tissue." (PMID 22550477, 2012). "The lack of association of ADRB3 Trp64Arg gene polymorphism with obesity and MetS in urban might be due to the complex pathogenesis of obesity and MetS, influenced by multigenes as well as the more contributing environmental factors." (PMID 21619577, 2011). "From a theoretical point of view, it seems plausible that altered function of ADRB3 may promote the development of obesity through enhanced lipid accumulation in white adipose tissue and decreased biological energy expenditure from brown adipose tissue as a result of decreased lipolysis." (PMID 21992420, 2011).
Obesity (continued). "Therefore, through its effect on energy expenditure of fat tissue, an impairment of ADRB3 function may lead to obesity." (PMID 21619577, 2011). "The results of the present study demonstrated that the polymorphism of ADRB3 alone does not increase the risk of obesity and that the environmental factor of high energy intake interacts with the polymorphism and leads to the significant increase in risk of obesity." (PMID 16276029, 2005). "Whereas the ADRB3 gene might influence the plasma levels of adipokines and lipids and the Trp64Arg polymorphism might be associated with obesity-related traits, it is not difficult to speculate that the Trp64Arg variant might influence the plasma levels of adipokines and lipids." (PMID 32430022, 2020). "Genetic variations in the obesity-related genes beta-2 adrenergic receptor (ADRB2), beta-3 adrenergic receptor (ADRB3), insulin induced gene 2 (INSIG2), and peroxisome proliferator-activated receptor gamma (PPARγ) are also included in our study." (PMID 22355322, 2012). "Recent human cohort studies have shown that Adrb3 expression in subcutaneous WAT is negatively correlated with the body mass index in women with or without obesity." (PMID 40362456, 2025). "In addition, p-synephrine was predicted to exert its anti-obesity effect via calcium and cAMP signaling pathways by targeting adrenergic receptors, ADRB1, ADRB2, and ADRB3." (PMID 34944408, 2021). "In addition, recent human cohort studies have revealed that Adrb3 expression in subcutaneous WAT derived from women with or without obesity is negatively correlated with body mass index (BMI)." (PMID 41009733, 2025).
diabetes (30 papers, 2009 to 2025). "We also assessed differences in variables related to diabetes between the BP groups and ADRB3 polymorphism groups using a two-way ANOVA." (PMID 34347822, 2021). "The Glu27 allele in ADRB2 and the Arg64 allele in ADRB3 are associated with abdominal obesity and early onset of non-insulin-dependent diabetes mellitus (NIDDM) in many ethnic groups." (PMID 22937051, 2012). "We have not evaluated the relationship between the incidence of diabetes and the ADRB3 polymorphism." (PMID 22550477, 2012).
overactive bladder (29 papers, 2015 to 2025). Symptom of overactive detrusor muscle of the urinary bladder that contracts with abnormally high frequency and urgency. "The aim of our study was to analyze the possible association between the ADRB3:rs4994 polymorphism and the patient-perceived response to a single intra-detrusor injection of botulinum toxin-A in Polish women with overactive bladder." (PMID 36556105, 2022). "These metaanalyses provide moderate epidemiological credibility for associations of variation in ADRB3 with overactive bladder, and variation of COL1A1 with prolapse." (PMID 25111588, 2015). "In pooled analysis, the rs4994 polymorphism of the ADRB3 gene was associated with overactive bladder (odds ratio [OR], 2.5; 95% confidence interval [CI], 1.7–3.6; n = 419)." (PMID 25111588, 2015). "These metaanalyses provide moderate epidemiological credibility for associations of variation in ADRB3 with overactive bladder, and COL1A1 with prolapse." (PMID 25111588, 2015). "Therefore, we decided to analyze the possible association between the ADRB3:rs4994 polymorphism and response at three months to a single intra-detrusor injection of botulinum toxin-A in Polish women with overactive bladder." (PMID 36556105, 2022). "Our results do not support the hypothesis that the ADRB3:rs4994 polymorphism is associated with the response to the intra-detrusor injection of botulinum toxin-A in female patients with overactive bladder." (PMID 36556105, 2022).